MBD1 (methyl-CpG binding domain protein 1)
Diseases named in the same sentence as MBD1 in open-access papers (continued):
Sharing a sentence is not in itself a finding about the gene and the disease.
infection (11 papers, 2011 to 2022). The state of being infected such as from the introduction of a foreign agent such as serum, vaccine, antigenic substance or organism. "Using a murine AVVC model, we described the kinetic response of mBD1 expression in the vaginal tract during C. albicans ATCC-36801 infection." (PMID 35049960, 2021). "The results showed a distinct profile of AMP induction depending on the strain origin, with an exacerbated mBD1+ expression when the infection was induced with the more virulent strain." (PMID 35049960, 2021). "Nevertheless, the percentage of mBD1-producing PMNs was higher when the infection was induced with a clinical strain." (PMID 35049960, 2021). "In the course of infection, it results in the attenuation of the secretion of murine beta-defensin-1 (mBD-1) in an animal model of infection, which was confirmed by a reduction in the expression of constitutively secreted hBD-1 in in vitro studies using the HT-29 cell line." (PMID 34831214, 2021). "However, in the viral and fungal models, deletion of mBD-1 alone had significant effects on infection." (PMID 33007818, 2020). "When this strain was injected into immunocompetent mBD-1-deficient mice, we observed a non-lethal disseminated infection." (PMID 33007818, 2020). "Alternatively, mBD-1 may serve an important role in preventing spontaneous infection or clearance of low bacterial inocula, but may be dispensable for bacterial clearance when mice are challenged with large bacterial inocula." (PMID 24204930, 2013). "Future work to elucidate the specific pathways controlled by MBD1 to regulate marginal zone B cell differentiation could enhance our understanding of marginal zone B cell mediated humoral immunity at homeostasis and in response to pathogen infection." (PMID 36574452, 2022). "By Day 7 after infection with WD3 in WT and with RB50 in mBD-1(−/−) mice, 1–2 neutrophils/field were observed." (PMID 30154362, 2018). "In mBD-1(−/−) mice, PMN influx was significantly diminished to 3 × 104 with WD3 infection." (PMID 30154362, 2018). "Murine mBD-1 mRNA and protein was down regulated while mBD-3, a homologue of hBD-2, was constitutively expressed in the murine rectal adenocarcinoma (CMT-93) cell lines after 24h post-infection." (PMID 25436887, 2013). "Similarly, expression of mBD-1 in neonatal BALB/c mice, constitutively expressed in uninfected control mice, was lowered at the peak of infection, at 4–7 days post infection." (PMID 25436887, 2013).
bacterial infections (3 papers, 2013 to 2020). "This is in contrast to the effect of mBD-1 deficiency on the susceptibility to Bordetella bronchiseptica bacterial infection, where a difference was only observed at 24 h." (PMID 33007818, 2020). "Mice with a deletion in the homologous mBD1 gene have an impaired capacity to combat bacterial infections, reflecting the importance of this AMP as a component of the innate anti-bacterial immune response." (PMID 23870035, 2013). "Initial experiments on those mice suggested that although mBD-1 may play a role in the initial stages of bacterial infection, the other β-defensins expressed in the airway may also contribute to the overall innate immune defense." (PMID 30154362, 2018).
diseases of the nervous system (2 papers, 2015 to 2017). "Regulatory mechanisms and diseases of the nervous system related to MBD1." (PMID 25751725, 2015).
inflammation (1 paper, 2012). Aberrant reaction of the microcirculation characterized by movement of fluid and leukocytes from the blood into extravascular tissues. "In both models of eosinophilic inflammation, down-regulation of the innate immune marker MBD-1 was observed." (PMID 22509389, 2012).
MBD1 also shares sentences with these, for which no sentence is quoted: leukemia (2 papers); viral infections (2); cerebral infarction (1); heroin addicts (1); peripheral nerve injury (1).